CASTOR2 (cytosolic arginine sensor for mTORC1 subunit 2)
Description:
Functions as a negative regulator of the TORC1 signaling pathway through the GATOR complex. As part of homodimers or heterodimers with CASTOR1, directly binds and inhibits the GATOR subcomplex GATOR2 and thereby mTORC1. Does not directly bind arginine, but binding of arginine to CASTOR1 disrupts the interaction of CASTOR2-containing heterodimers with GATOR2 which can in turn activate mTORC1 and the TORC1 signaling pathway.
Synonyms: GATSL1; GATSL2
Tractability: PROTAC: ubiquitination databases record sites on it.
Gene: Protein-coding gene on chromosome 7 (74,964,705 to 75,031,528, forward strand). Ensembl gene ENSG00000274070.
Subcellular location: Cytoplasm, cytosol
Pathways (Reactome):
Cellular responses to stimuli: Amino acids regulate mTORC1
Gene Ontology:
Molecular function: arginine binding; identical protein binding; protein binding
Biological process: cellular response to L-arginine; negative regulation of TORC1 signaling
Cellular component: cytosol; GATOR2 complex
Genetic constraint (gnomAD): Loss-of-function variants: 8 observed, 31.73 expected, observed/expected ratio (o/e) 0.25, 90% interval 0.15 to 0.46. The upper end of that interval is the gene's LOEUF score, 0.46, which puts it in group 2 of 6, group 1 being the genes least tolerant of losing a copy. Missense variants: 216 observed, 391.71 expected, observed/expected ratio (o/e) 0.55, 90% interval 0.49 to 0.62. Synonymous variants: 162 observed, 165.08 expected, observed/expected ratio (o/e) 0.98, 90% interval 0.86 to 1.12.
Homologues: Orthologues: chimpanzee CASTOR2 (100% identical), macaque CASTOR2 (100% identical), pig CASTOR2 (99% identical), rat Castor2 (98% identical), mouse Castor2 (97% identical), guinea pig CASTOR2 (96% identical), tropical clawed frog castor2 (88% identical), dog CASTOR2 (86% identical), rabbit CASTOR2 (83% identical), zebrafish castor2 (83% identical). Paralogues in human: CASTOR1 (63% identical).
Diseases named in the same sentence as CASTOR2 in open-access papers:
CASTOR2 is named in the same sentence as 10 diseases in open-access papers, as found by Europe PMC text mining. Sharing a sentence is not in itself a finding about the gene and the disease. The quoted sentences say what the papers report.
gastric cancer (1 paper, 2023). A primary or metastatic malignant neoplasm involving the stomach. "In gastric cancer, both CASTOR2 and MXD4 expression levels were inversely correlated with MYEOV expression levels." (PMID 36698109, 2023).
muscular atrophy (1 paper, 2022). The loss of muscle tissue due to inactivity or disease. "In this sense, CASTOR2, among other genes, has been described as a target of the proteolytic pathway of FoxO driving to muscular atrophy." (PMID 35897722, 2022).
pancreatic cancer (1 paper, 2023). "Conversely, in pancreatic cancer cells, MYEOV expression is upregulated and promotes the downregulation of MXD4 and CASTOR2, resulting in the activation of c-Myc and mTORC1 and tumor progression." (PMID 36698109, 2023).
tumor (2 papers, 2023). "Because previous studies have reported that RNA binding motif protein 47 (RBM47), zinc finger protein 621 (ZNF621), and cytosolic arginine sensor for mTORC1 subunit 2 (CASTOR2) function as tumor suppressors, we selected these genes for further verification." (PMID 37981573, 2023).
CASTOR2 also shares sentences with these, for which no sentence is quoted: cancer (1 paper); cardiac hypertrophy (1); Kaposi's sarcoma (1); lung adenocarcinoma (1); Lung Squamous Cell Carcinoma (1); spinal cord glioma (1).